VDR (vitamin D receptor)
Diseases named in the same sentence as VDR in open-access papers (continued):
Sharing a sentence is not in itself a finding about the gene and the disease.
breast cancer (continued). "Some studies have shown that there is a link between VDR levels and recurrence of breast cancer, tumour size, and death from breast cancer as recently reported in melanoma." (PMID 25849303, 2015). "In breast cancer, the regulation of VDR expression and activity by estrogens is likely to be clinically significant." (PMID 24982636, 2014). "Genomic profiling has characterized many 1α,25(OH)2D3 responsive targets in normal mammary cells and in breast cancers providing valuable insight into the molecular actions of 1α,25(OH)2D3 and the VDR in regulation of cell cycle, apoptosis and differentiation." (PMID 24982636, 2014). "Genomic profiling has characterized many 1α,25(OH)2D3 responsive targets in normal mammary cells and in breast cancers, providing insight into the molecular actions of 1α,25(OH)2D3 and the VDR in regulation of cell cycle, apoptosis, and differentiation." (PMID 24982636, 2014). "Analysis of the TCGA invasive breast cancer dataset of over 450 breast tumors suggests that alterations in the VDR gene are rare in human breast cancer." (PMID 24982636, 2014). "The associations between vitamin D receptor (VDR) gene polymorphisms and breast cancer risk were comprehensively investigated to clarify issues that remain controversial." (PMID 24769568, 2014). "Experimental studies on mammary tumor cell lines from VDR-knockout mice have shown that VDR is necessary for 1,25(OH)2D to induce cell cycle arrest and apoptosis in breast cancer cells." (PMID 24252436, 2014). "In vivo, both high dietary vitamin D and treatment with synthetic VDR agonists inhibit the development of carcinogen induced mammary tumors." (PMID 24982636, 2014). "Numerous studies have profiled the cellular and molecular effects of 1,25(OH)2D3 on VDR positive breast cancer cells." (PMID 24982636, 2014). "Animal models of established breast cancer have demonstrated that VDR agonists can reduce tumor growth (and in some cases trigger tumor regression) with minimal effects on calcemia [the most common and dangerous side effect of 1,25(OH)2D3 therapy]." (PMID 24982636, 2014). "VDR expression is retained in the majority of rodent breast tumors, human breast cancers and established breast cancer cell lines." (PMID 24982636, 2014). "In general, the effects of VDR agonists on breast cancer cells include modulation of key cell cycle regulators to induce G0/G1, induction of differentiation markers, and/or activation of cell death (via apoptosis or autophagy)." (PMID 24982636, 2014). "The functions of CYP27B1 and VDR in prevention of breast cancer are supported by data from animal models." (PMID 24982636, 2014). "Our study identifies that the 5-year disease-free-survival from breast cancer is significantly reduced among breast cancer patients with the VDR-FokI FF genotype (Log rank = 6.06 and p = 0.05)." (PMID 23554871, 2013). "Kaplan-Meier survival analysis showed decreased 5-year disease-free-survival (DFS) in breast cancer patients who had the VDR-Fok1 FF genotype (p<0.05)." (PMID 23554871, 2013). "Poorly differentiated (ER−) breast cancer cell lines express less VDR and are less sensitive to 1,25D administration." (PMID 23341935, 2013). "VDR is expressed both in normal and transformed mammary cells and the vitamin D signaling pathway has potential protective effects against breast cancer tumorigenesis." (PMID 23382798, 2013). "The link between vitamin D and breast cancer is based on the concept that the vitamin D receptor (VDR) and its ligand 1,25D (the biologically active form of vitamin D) promotes or maintains the differentiated phenotype in normal mammary cells." (PMID 24171049, 2013). "Our results indicate that mammospheres isolated selectively from established breast cancer cells have suppressed VDR signaling, increased expression of CD44, and decreased sensitivity to 1,25D administration." (PMID 23341935, 2013).
breast cancer (continued). "VDR ablation also enhanced the tumorigenesis for the MMTV-neu transgenic model of breast cancer with shortened latency, increased incidence of mammary tumor formation and worse prognosis." (PMID 23382798, 2013). "An important finding of this study was the down-regulation of VDR/RXR in the mammospheres from breast cancer cell lines when compared to differentiated cells grown on high attachment plates." (PMID 23341935, 2013). "Several studies have demonstrated a decrease in Vitamin D receptor (VDR) expression in breast cancer cells compared to normal breast cells." (PMID 23554871, 2013). "We next examined expression of VDR in breast cancer cells grown as mammospheres or as more differentiated cells grown on high attachment plates." (PMID 23341935, 2013). "Therefore, dietary factors may influence the association of VDR genotypes with breast cancer risk." (PMID 23533810, 2013). "Although there are reports that VDR levels are low in aggressive TN breast cancer cell lines, to our knowledge, this is the first report demonstrating the suppression of this receptor in mammospheres." (PMID 23341935, 2013). "Calcitriol therapy seems promising especially for breast cancer, since malignant ductal epithelial cells generally express VDR, as shown in this and other studies." (PMID 22984610, 2012). "For instance, activation of the p38 and JNK MAPK pathways in breast cancer cells was found to increase VDR expression via upregulation of AP-1 which can bind to and transactivate the VDR gene promoter." (PMID 23259067, 2012). "In the human mammary gland, VDR is expressed in all cell types, and vitamin D treatment inhibits breast cancer cell proliferation, induces cell apoptosis, and prevents carcinogenesis in rodent models." (PMID 22480149, 2012). "Instead, we evaluated variants in vitamin D activity and major metabolism (VDR, CYP27B1, and CYP24A1) in relation to breast cancer risk, particularly in relation to self-reported race and estrogen receptor status." (PMID 22480149, 2012). "For colon and breast cancer cells, an inverse relationship between VDR levels and degree of differentiation has been described." (PMID 23094155, 2012). "Herein we suggest a novel combined adjuvant therapy for the management of VDR/Eag1-expressing breast cancer tumors." (PMID 22984610, 2012). "VDR and Eag1 presence and bioactivity in breast cancer cells are; therefore, predictors to calcitriol and astemizole response, independently of estrogen or growth factor receptors status, as shown herein." (PMID 22984610, 2012). "Krishnan and Feldman showed that VDR expression in a breast cancer cell line was upregulated by stimulation with a combination of serum and growth factors." (PMID 23346460, 2012). "The G allele of Cdx2 was associated with lower risk of breast cancer in AA women in our study and this finding was in contrast to the speculated functional alteration that the variant G allele resulted in lower binding of the Cdx2 protein and thus lower transcriptional activity of VDR." (PMID 22480149, 2012). "The focus of this study was to investigate the antiproliferative and proapoptotic activities of MART-10 in the ER+ MCF-7 breast cancer cells which express high level of VDR." (PMID 23304196, 2012). "Our data provide scientific bases for further pharmacodynamic and pharmacokinetic studies designed to test both compounds simultaneously in subjects affected with breast cancer, particularly those expressing VDR and Eag1." (PMID 22984610, 2012). "Some studies have demonstrated that the VDR protein is expressed in samples from normal breast tissues and also in breast cancer biopsy specimens." (PMID 20831823, 2010). "Immunohistochemical studies have confirmed that the VDR is expressed in samples from normal breast tissues and also in breast cancer biopsy specimens." (PMID 20831823, 2010).
breast cancer (continued). "Vitamin D exerts most of its biological activities by binding to a specific high-affinity receptor, the Vitamin D Receptor (VDR), that was first identified in a breast cancer cell line in 1979." (PMID 20831823, 2010). "A fully characterized series of 189 breast carcinomas in situ arranged in 22 TMAs was assessed for the expression patterns of VDR, CYP27B1 and CYP24A1." (PMID 20831823, 2010). "VDR145+/+ and VDRK240−/− cell lines are derived from DMBA-induced mouse mammary tumors from wild-type (WT) and VDR knockout (KO) mice, respectively and were described previously." (PMID 19924301, 2009). "On the basis of these findings, there has been considerable interest in the therapeutic use of VDR agonists in the treatment of breast cancer." (PMID 19442290, 2009). "We found that TCF-4 is differentially expressed in cells derived from DMBA-induced mouse mammary tumors from VDR wild-type and knock out mice, and the mammary glands themselves." (PMID 19924301, 2009). "Our research does not support an independent association between selected polymorphisms in the VDR, GC, or CYP24A1 genes and postmenopausal breast cancer risk among US Caucasian women." (PMID 17244366, 2007). "In fact, the vitamin D-receptor has been reported to be present in 80% of breast cancers and to be expressed at significantly higher concentrations in breast cancers than in normal breast tissue." (PMID 16542425, 2006). "The VDR was expressed in 95% of the tumors as expected, with mRNA levels of 1 ± 0.09 and 1.4 ± 0.12 (p < 0.05) in breast cancer and normal breast, respectively." (PMID 16280049, 2005). "Here we have determined expression levels of 1α-hydroxylase, 24-hydroxylase and VDR in breast cancer cells and demonstrated the activity of a non-1α-hydroxylated vitamin D analogue." (PMID 16280049, 2005). "In breast cancer cells, 1α,25 (OH) 2D3 has been found to inhibit tumor proliferation by binding to VDR, In ovarian cancer cells, 1,25 (OH) 2D3 upregulates p27 protein levels, inhibits cyclin E/CDK2 activity, leading to cell cycle arrest at G1 phase and suppression of proliferation." (PMID 41031356, 2025). "VDR expression and clinicopathological features in patients with breast carcinoma." (PMID 40898467, 2025). "There are numerous studies investigating the relationship between breast carcinoma and VDR." (PMID 40898467, 2025). "The significant findings obtained in our study between VDR expression and triple-negative patients as well as ER, PR, and Ki-67 results may offer beneficial approaches for the management of breast carcinomas at all stages." (PMID 40898467, 2025). "It is interesting to note that treating two TNBC breast cancer cell lines with a VDR agonist and an AR agonist decreased cell viability; when combined, they appeared to be additive, and viability was decreased further when the agonists were combined with chemotherapeutic drugs." (PMID 39273194, 2024). "A number of clinical studies have demonstrated that higher expression of VDR is positively correlated with better prognosis or low TNM stage in breast cancer, colorectal cancer, papillary thyroid cancer, lung cancer, urothelial bladder cancer, and childhood solid tumors." (PMID 38639057, 2024). "If confirmed, VDR genotypes may be used to more refined tailoring of adjuvant breast cancer treatment." (PMID 38351438, 2024). "An unexpected result was the lack of an association between the VDR SNPs and ER status since two studies have shown that the Taq1 polymorphism was associated with a higher frequency of ER+ breast cancer." (PMID 38351438, 2024). "There is crosstalk between the VDR and ER signaling as seen from studies of breast cancer cells." (PMID 39273194, 2024).
breast cancer (continued). "Further studies are suggested to confirm our results and to evaluate whether VDR should and could be used as a prognostic and targetable marker in breast cancer diagnostics." (PMID 38612962, 2024). "The secondary aim was to explore whether the subcellular localization of VDR yields refined prognostic information in breast cancer." (PMID 38612962, 2024). "Consequently, the VDR emerges as a pivotal target meriting consideration in strategies aimed at breast cancer prevention." (PMID 38440355, 2024). "Therefore, in this novel and innovative study, we explored the most possible action of quercetin on breast cancer-induced liver inflammation and fibrosis via VDR." (PMID 37153919, 2023). "Dietary flavonoid, quercetin could act as a promising therapeutic drug to suppress the breast cancer induced tumor angiogenesis, hepatic inflammation, and fibrosis possibly via activation of VDR." (PMID 37153919, 2023). "VDR polymorphisms have been reported to be associated with altered disease risk, including breast cancer, non-melanoma skin cancer, and an array of tobacco-related cancers." (PMID 36975461, 2023). "A recent study showed that VDR acts as a possible therapeutic target for breast cancer." (PMID 37153919, 2023). "Breast cancer cell lines were analyzed for VDR, Brk and involucrin expression by Western blotting." (PMID 37445934, 2023). "The most prevalent DEGs connected with WikiPathways route include retinoblastoma gene in cancer, G1 to S cell cycle control, cell cycle, DNA IR-damage and cellular response via ATR, miRNA regulation of DNA damage response, vitamin D receptor pathway, and integrated breast cancer pathway." (PMID 36723760, 2023). "As with other nuclear receptors, expression of VDR is often dysregulated in breast cancer." (PMID 37583424, 2023). "In addition, VDR is found in some tumour tissues, such as breast cancer, oesophageal cancer, and colorectal cancer." (PMID 37561808, 2023). "Thus, our studies fill these gaps in knowledge by investigating the mechanisms by which intestinal epithelial VDR regulates the development of breast cancer." (PMID 37074210, 2023). "According to many studies, hypovitaminosis D in breast cancer could also be explained by the presence of VDR, because its expression in BC tissue decreases during tumour progression, making it less sensitive to vitamin D3." (PMID 38132250, 2023). "A recent study examined the relationship between intestinal Vitamin D receptor (VDR) and breast cancer, specifically investigating whether an intestinal‐microbiome‐breast axis exists." (PMID 37539732, 2023). "However, this study has some limitations, such as a lack of an evaluation of the enzymes 1α-hydroxylase, 24-hydroxylase, and the VDR in breast cancer tissue samples." (PMID 38132250, 2023). "Our current study fills the gaps in knowledge by revealing a previously unknown mechanism by which intestinal epithelial VDR is important for normal host homeostasis and protects against breast cancer." (PMID 37074210, 2023). "VDR expression level in breast tumor tissue microarrays has shown inversely associated with aggressiveness of breast cancer, but not with cancer survival outcomes." (PMID 37074210, 2023). "In addition, VDR expression can be used as a biomarker to predict sepsis mortality and bone metastasis of breast cancer." (PMID 36829206, 2023). "It was recently found that cytoplasmic VDR can potentiate the growth of breast cancer cell lines in the absence of ligand altogether, suggesting a ligand-independent function for VDR that has yet to be fully understood in the context of breast cancer formation and treatment resistance." (PMID 37583424, 2023). "Additionally, breast cancer cell lines showed an increase in VDR methylation levels than normal cells." (PMID 38203278, 2023). "The vitamin D receptor is commonly expressed in breast tissues, as well as in breast cancer cells." (PMID 36986179, 2023).
breast cancer (continued). "A possible explanation of how vitamin D might affect breast cancer biology might be the tumor suppressive effects of vitamin D receptor catabolism, as a defect in the vitamin D receptor (e.g., CYP27B1 and CYP24A1 regulation) led to decreased signaling." (PMID 36986179, 2023). "Furthermore, VDR-targeted agonists, such as calcitriol, seemed to inhibit the proliferation of triple-negative and VDR-positive breast cancer cells, supporting the tumor-suppressing effect of VDR." (PMID 37345127, 2023). "Therefore, ZCyd was able to inhibit the epigenetic silencing of VDR and restore calcitriol sensitivity of breast cancer cell lines, thus representing a potential drug in anti-cancer therapy." (PMID 38203278, 2023). "Breast cancer cells, depending on origin, can be inherently vitamin D3 resistant or sensitive or acquire resistance during disease progression due to various effects, including methylation of the VDR promoter." (PMID 35328609, 2022). "To conclude, there was no statistical evidence for an association between pre-diagnostic levels of vitamin D and the expression of VDRs in breast cancer, nor did vitamin D levels influence the association between VDR expression and breast cancer mortality." (PMID 36014861, 2022). "Collectively, these findings prompted us to evaluate the function of ERRα in the deregulation of the VDR signaling network in breast cancer in vitro and through a bioinformatics approach to explore the relevant interactions underlying the biological behavior of ERRα." (PMID 34003583, 2022). "Several lncRNAs have been identified to modulate VDR signaling in breast cancer." (PMID 35328609, 2022). "This manuscript summarizes and updates information on the effects of vitamin D3/VDR in breast cancer, the mutual interaction between vitamin D3/VDR and lncRNAs, and the role lncRNAs may play in the effects of vitamin D in breast cancer pathogenesis." (PMID 35328609, 2022). "We hypothesize that women with habitually higher levels of vitamin D could develop breast cancers that are more often VDR positive." (PMID 36014861, 2022). "Still, a study population of 497 women with breast cancer remained, but since there is a probable pattern of missingness at random of both levels of vitamin D and VDR expression we choose to perform multiple imputations to also include women with missing values in the statistical analyses." (PMID 36014861, 2022). "Pre-diagnostic levels of vitamin D did not alter the association between VDR expression in a breast tumor and a favorable breast cancer prognosis." (PMID 36014861, 2022). "By binding to the VDR, 1,25(OH)2D3 regulates calcium and phosphate homeostasis in the body, and, additionally has potent antiproliferative and pro-differentiating actions on various normal as well as cancerous cell types such as breast cancer (BC) cells." (PMID 35784555, 2022). "The general conclusion from these studies is that VDR may act as a tumor suppressor whose regulation is impaired in breast cancer transformation." (PMID 35328609, 2022). "Moreover, non-steroid nuclear receptors, including the vitamin D receptor (VDR) and the thyroid receptors (TRs), are also present in breast cancers and have pathophysiologic implications." (PMID 35160139, 2022). "It was shown that the vitamin D/VDR axis in breast cancer is regulated by many miRNAs." (PMID 35328609, 2022). "Another study within the MDCS cohort showed that patients with invasive tumors expressing a high fraction of nuclear VDR had a relatively low breast cancer-specific mortality, i.e., a good survival, and were associated with favorable tumor characteristics, such as ER expression." (PMID 36014861, 2022).